CXCL12 (C-X-C motif chemokine ligand 12)
Diseases named in the same sentence as CXCL12 in open-access papers (continued):
Sharing a sentence is not in itself a finding about the gene and the disease.
tumor (continued). "Moreover, tumor treatment with tranilast inhibits infiltration of TAMs by suppressing secretion of CXCL12, significantly promoting infiltration of CD8+ lymphocytes into the tumor and leading to apoptosis of cancer cells through an immune response." (PMID 40453088, 2025). "In line with our observations, SPHK1 expression relative to CXCR4 as well as CXCL12 relative to S1PR5 correlated positively in tumor biopsies but not in the respective normal control tissue." (PMID 40155684, 2025). "Moreover, MMP2 was overexpressed in the early and late stages of tumor progression in the stromal area, and CXCR4 and CXCL12 were enriched after mid-stage progression inside the tumor." (PMID 39965034, 2025). "In addition, authors observed that the expression levels of both CXCL12 and CXCR7 were elevated in metastatic samples compared to primary tumor tissues." (PMID 40943634, 2025). "The CXCL12/CXCR4 axis, crucial in cancer progression and immunosuppression, involves CXCL12 from CAFs recruiting CXCR4-expressing cells that support angiogenesis and tumor growth." (PMID 40313969, 2025). "In contrast, CXCL12’s ability to recruit immune cells and other cell types may shape the TME, impacting tumor development and treatment response." (PMID 41584584, 2025). "In addition, CXCL12/CXCR4 signalling encourages angiogenesis and tissue remodelling, resulting in increased tumour vascularisation and increased potential for metastatic spread." (PMID 41002447, 2025). "The CXCL12/CXCR4 axis participates in numerous cellular functions, including cell proliferation, migration, and differentiation, and has been thoroughly investigated in several tumours and autoimmune diseases." (PMID 39779470, 2025). "Molecular profiling of tumor tissue or exosomes for neurotrophic factors (NGF, BDNF, GDNF), chemokines (CXCL12, CCL2), or neuronal transcription factors (POU4F1) may serve as predictive biomarkers of neural involvement." (PMID 41009819, 2025). "The interaction between CXCL12 and CXCR4 promotes tumor growth and metastasis." (PMID 41439026, 2025). "The homing mechanism is facilitated by MSC surface expression of key chemokine receptors, including CXCR4 and CCR2, which detect and respond to chemotactic gradients established by tumor-secreted factors such as SDF-1, MCP-1, and CXCL12 within the tumor microenvironment." (PMID 41301162, 2025). "We detected CXCL12 expression in the stroma of eight of the nine canine tumor histo-types examined, with no detectable expression in anal sac gland carcinoma." (PMID 40849508, 2025). "exp‐CAF2‐shENG cells also showed attenuated mRNA expression levels of α and β alternative splicing forms of CXCL12/stromal cell‐derived factor‐1 (SDF‐1), which could mediate CAF‐promoted primary tumor growth based on our previous studies." (PMID 40644310, 2025). "The CXCL12/CXCR4 axis is indeed a critical pathway for CD8+ T cell trafficking, but emerging evidence underscores the importance of complementary chemokine axes that contribute to immune cell recruitment and spatial coordination in the tumor microenvironment." (PMID 40698080, 2025). "Senescent endothelial cells consequently release SASP factors, which contribute to tumor cell recruitment and metastasis to liver, and in the SASP secreted by senescent endothelial cells, the chemokine CXCL12 is critical for senescent endothelium leading to tumor cell migration (Graphic Abstract)." (PMID 38951874, 2024). "Notably, treatment-induced tumor volume reduction correlated with decreased levels of CCL-2, CCL-7, and CCL-12 and increased levels of CXCL-10, CCL-24, CXCL-12, and IL-3." (PMID 38575562, 2024). "The CXCL12/CXCR4 axis can modulate the immune microenvironment of tumors by attracting regulatory T cells (Tregs) and myeloid-derived suppressor cells (MDSCs), which suppress anti-tumor immune responses." (PMID 39682247, 2024). "Similarly, targeting CXCL12-producing fibroblasts unleashed CD8+ T cell immunity and persistent tumor control." (PMID 39107856, 2024).
tumor (continued). "Additionally, residual M2-type TAMs aggregate in the perivascular region through the CXCR4/CXCL12 pathway, secreting factors like VEGF to further facilitate tumor revascularization and recurrent metastasis." (PMID 39531417, 2024). "The expression levels of ccl-2 (MCP-1), ccl-20 (MIP-3), ccl-7 (MCP-3), CXCL-4 (PF-4), CXCL 1 (Gro -), and CXCL-12 (SDF-1) are also significantly increased in replicative senescent cells, allowing the disruption of the blood-tumor barrier integrity and greater spread of tumor cells." (PMID 37450933, 2024). "The secretion of CXCL12 recruits regulatory T cells (Tregs), leading to Treg infiltration and increased TGF-β secretion in the microenvironment and promotes the formation of a tumor immunosuppressive microenvironment." (PMID 38287007, 2024). "Tumor cells promote the migration of myeloid-derived suppressor cells (MDSCs) and macrophages into the tumor microenvironment by secreting chemokines such as CCL2, CCL5, and CXCL12." (PMID 39717759, 2024). "In addition to targeting CXCR4, the anti-tumor effects of NOX-A12 (olaptesed pegol), an L-RNA aptamer inhibitor of CXCL12, have been evaluated in combination with anti-PD1." (PMID 38339310, 2024). "Certain chemokines (such as CXCL9 and CXCL10) can promote anti-tumor immune responses, while others (like CCL2 and CXCL12) may facilitate tumor progression." (PMID 39030403, 2024). "Recent studies have shown that the CXCR4 antagonist AMD3100, also known as plerixafor (Marketed Mozobil® (Sanofi, Paris, France)), effectively blocks the CXCL12/CXCR4 interaction, thereby inhibiting the migration of Tregs and other immune cells within the tumor microenvironment." (PMID 39273290, 2024). "High CXCL12 expression in tumors may desensitize tumor cells expressing CXCR4 receptors, thus preventing tumor proliferation." (PMID 38767772, 2024). "Furthermore, blockade of CXCL12/CXCR4 pathway prolonged the survival of tumor-bearing mice and reduced tumor burden in several preclinical studies." (PMID 39003350, 2024). "Furthermore, the interaction between fibroblast-derived CXCL12 and CXCR4 on tumor cells and monocytes also decreased notably following IGF2 loss." (PMID 39545420, 2024). "To investigate if factors in the tumor microenvironment mediate the MDMX-dependent upregulation of CXCR4, we explored if adding the stromal-derived extracellular signaling chemokine CXCL12 to cells grown in a culture would recapitulate the results observed in the xenograft tumors." (PMID 39766093, 2024). "Administering CXCL12 in vivo inhibited mouse HCC progression, and this anti‐tumor effect could be abrogated by a CXCR4 inhibitor." (PMID 39422063, 2024). "On PDTs, VACV GM-CSF+ could induce downregulation of other proteins involved in tumoral progression, such as CX3CL1 and CXCL12 chemokines." (PMID 38698850, 2024). "Given that MMP-9 is able to degrade the ECM, which is an essential step in tumor cell extravasation and metastasis, and it is highly expressed in PDAC, CXCL12 may be playing a similar role in upregulating MMPs in PDAC." (PMID 38339310, 2024). "Moreover, CD44, CXCL12 and TGFBR2 were positively correlated with all tumor infiltrating immune cells." (PMID 38877052, 2024). "The presented results indicate the significant correlation between the CXCL12, CXCR4, CXCL8/CXCR2, M-CSF, MMP-2, MMP-9 ADAM17, ADAMTS-6, and CLDN7 levels and tumor stage, as well as the clinicopathological parameters of OC, such as the presence of lymph node and/or distant metastases." (PMID 38673838, 2024). "In our previous studies, we investigated whether serum CXCL12 and its specific receptor (CXCR4) levels may be used as potential biochemical tumor markers for OC." (PMID 38673838, 2024). "Additionally, the potential for leveraging the upregulation of CXCL12 and the subsequent activation of the STAT3 pathway to prevent tumor metastasis warrants further investigation." (PMID 38920657, 2024).
tumor (continued). "Since CXCL12 is mainly expressed in spinal cord astrocytes after tumor cell implantation, intrathecal injection of astrocyte inhibitor or selective JNK inhibitor can block the tumor cell implantation induced by high expression of CXCL12 in the spinal cord." (PMID 39641645, 2024). "In summary, by interfering with the AR/FlnA complex, targeting several extracts, and inhibiting the activity of key factors, such as YAP1, CXCL12, and TGF-β, the pro-tumor function and ability to maintain the CAF tumor can be effectively impaired, providing a new approach for PCa treatment." (PMID 39092186, 2024). "CXCL12 promotes tumor angiogenesis by targeting vascular endothelial cells and cooperating with vascular endothelial growth factor (VEGF), and also promotes tumor cell proliferation and survival." (PMID 39654896, 2024). "We further analysed the correlation between CXCL12, CD44v6, HIF1A, TGFBR2 and KRT7 expression in metastatic tumor tissues & exosomes with sex, age, habit, Tumor Differentiation grade, TNM stage, EGFR mutation status, AE1, Chromogranin, CDX2, CEA, CK20, TTF-1 & CK7." (PMID 38877052, 2024). "Tumor stromal cells can also induce infiltration of MDSCs by secreting CCL2 and CXCL12." (PMID 38397901, 2024). "However, subsequent to the confirmation of ACKR3 as a receptor of CXCL12, a plethora of studies have verified that the binding of CXCL12 and ACKR3 can also activate the STAT3 pathway, thereby fostering tumor development." (PMID 38920657, 2024). "MDSCs express several chemokine receptors such as CCR2, CXCR2, CXCR4, and CXCR5, while liver tumor cells or malignant hepatocytes express chemokines such as CCL2, CCL5, CXCL1, CXCL5, and CXCL12, and the chemokine/its receptor axis mediates MDSC infiltration in the tumor microenvironment." (PMID 38397901, 2024). "In agreement, senescent fibroblasts express various proliferation-inducing factors (e.g. HGF, CXCL12 and EGF), can induce treatment resistance via inducing tumor cell EMT, or metabolically support tumor cell progression and metastasis by upregulating glycolysis and ketone production." (PMID 39696386, 2024). "Additionally, the co-culture of ASCs with melanoma cells upregulates the expression of CXCL12/13 and CCL2, further promoting the recruitment of ASCs to the tumor microenvironment." (PMID 39519109, 2024). "Tumor’s progression is marked by an increase in the IFF that plays a critical role in GBM cells migration through increasing their expression of CXCR4 and secretion of CXCL12 along white matter tracts, blood vessels, and subpial regions." (PMID 39715221, 2024). "The OPN-driven CAFs then secrete CXCL12, which in turn triggers EMT in the tumor cells." (PMID 39335478, 2024). "The expression of hypoxia-related chemokines, such as CXCL12 and CXCL8, along with pro-angiogenic factors such as vascular endothelial growth factor (VEGF), produced and expressed simultaneously by tumor cells and the breast stroma, promotes the formation of abnormal vessels in tumors." (PMID 39769501, 2024). "In addition, tumor cell-derived conditioned medium (CM) containing abundant extracellular vesicles also increased α-SMA, FAP, IL-1, IL-6, IL-8, CCL5 and CXCL12 expression and enhanced the proliferation, motility and invasion of ADSCs." (PMID 38233863, 2024). "Moreover, CXCR4 and CCR7 interact with their respective ligands chemokine (C-X-C motif) ligand 12 (CXCL12) and chemokine (C-X-C motif) ligand 21 (CCL21), enabling tumor cells to have “chemotaxis” and promoting their metastasis to the intended organs." (PMID 38549934, 2024). "Additionally, chemokines like CXCL12 play a role in recruiting immunosuppressive cells to the TME, enhancing the tumor’s ability to resist immune attack." (PMID 39200315, 2024). "Likewise, CXCL13 and CXCL1 foster tumor development via the AKT signaling pathway, additional chemokines such as CXCL14, CXCL3, and CXCL12 serve as predictive factors." (PMID 38844562, 2024).
tumor (continued). "Furthermore, the interaction between MM cells and cancer-associated fibroblasts (CAFs) via adhesion molecules such as CXCL12/CXCR4 and integrins is essential for promoting CAFs’ tumor-supporting functions." (PMID 38560563, 2024). "Furthermore, GB cells secrete stromal-derived factor-1 (SDF-1/CXCL12), which plays a crucial role in the recruitment of BM-MSCs into the tumor blood vessels." (PMID 38396962, 2024). "By utilizing a conditional CXCL12 knockout murine model, we demonstrate that endothelial-specific deletion of CXCL12 (eKO) modulates ischemic tissue survival, altering tissue repair and tumor progression without affecting embryogenesis and morphogenesis." (PMID 39698751, 2024). "Notably, our computational analysis of this high-dimensional data suggests that the key changes correlating with inhibition of tumor growth include the downregulation of CCL-2, CCL-7, CCL-12, and the upregulation of CXCL-10, CCL-24, CXCL-12 and IL-3." (PMID 38575562, 2024). "In addition to chemotaxis, CXCL12 and CXCR4 can induce monocyte differentiation into TAMs, which significantly increases tumor invasiveness." (PMID 39606239, 2024). "Chemoattractants, produced by malignant cells and the stromal tumor compartment, such as C-C Motif Chemokine Ligand 2 (CCL2), vascular endothelial growth factor (VEGF), CXCL12 (SDF1) and colony-stimulating factor-1 (CSF-1), recruit monocytes from the bloodstream that migrate into tumor site." (PMID 38397187, 2024). "Furthermore, CXCL2, CXCL12, CCL2, and CXCL8 in humans have each been observed to regulate G-MDSC recruitment to the tumor microenvironment." (PMID 37988164, 2024). "On the other hand, CXCL12 displayed a negative correlation with 18 tumors and a positive correlation with one tumor." (PMID 39068665, 2024). "Furthermore, the CXCL12/CXCR4-AKT axis activates the downstream RhoA/ROCK2 pathway, which modulates cell invasion and tumor metastasis." (PMID 39766093, 2024). "This compartmentalized expression pattern of CXCL12 and CXCR4 indicates that the KS PDX system will be useful to further delineate the communication networks that promote proliferative expansion of KS infected endothelial cells in the tumor microenvironment." (PMID 39386738, 2024). "Additionally, CXCL12, secreted by FAP+ CAFs, further inhibits the accumulation of cytotoxic T cells near the tumor, contributing to immune evasion in PDAC." (PMID 38540204, 2024). "This shift from CCL5/CXCL9/CXCL10 to CXCL8/CXCL12/CCL22 production was attributed to NFκB-mediated induction of COX2/PGE2/EP4, along with upregulation of IDO1 and IL-10, further contributing to the immunosuppressive tumor microenvironment." (PMID 39409924, 2024). "In addition, preclinical studies showed that both pharmacological inhibition of CXCR4 and genetic ablation of CXCL12-producing CAFs led to a rapid accumulation of CD8+ T cells within the tumor and reduced tumor growth." (PMID 38182756, 2024). "Other genes were down-regulated in tumour versus adjacent tissue, most prominently CXCL12 (20.6-fold in patients without DMI and 21.7-fold in patients without LVI), followed by TIMP3 (15.0-fold in DMI absent and 16.2-fold in LVI-absent EC)." (PMID 37509322, 2023). "CXCL10, CXCL5, MMP1, CXCL12, CXCL11, CXCL2, STAT1, IL‐6 and TLR2 were hub genes in network and may promote or inhibit the homing or of immune cells in tumours and immune cell differentiation, bring intratumoral immune heterogeneity." (PMID 36524848, 2023). "Among these genes, we identified several factors that were related to tumor progression and were found to be consistent with previously reported, for example, CAT, ATP1B1, CCND1, and CXCL12." (PMID 38020927, 2023). "Except for CXCR6, all cytokines/cytokine receptors were shown to operate in the spine, with CX3CL1, CX3CR1, IL10, CCL2, CXCL12, and CXCR4 mediating bone marrow colonization, CXCL5 and TGFβ promoting tumor cell proliferation, and TGFβ additionally driving bone remodeling." (PMID 36835198, 2023).
tumor (continued). "We investigated whether the CXCL12/CXCR4 axis-mediated transformation of ADMSCs promotes the migration and invasion ability of MCF7 cells and whether curcumin reverses this tumor-promoting effect." (PMID 38004606, 2023). "In addition to cell mobilization from BM, the CXCL12/CXCR4/CXCR7 axes can participate in the growth and development of tumor cells and angiogenesis." (PMID 38260135, 2023). "In premenopausal patients (n = 11), six genes were statistically significantly down-regulated in tumour tissue compared to tumour-adjacent tissue: TIMP3 (13.1-fold), ENPP2 (11.4-fold), FGF2 (7.6-fold), CXCL12 (7.5-fold), TIMP2 (5.2-fold), and PDGFRB (4.9-fold change)." (PMID 37509322, 2023). "Irradiated tumor tissues and cancer cells recruit chemokines such as CCL22 and CXCL12 and produce a range of cytokines such as TNF-α, TGF-β, IL-1, IL-6, and GM-CSF which could recruit tumor-infiltrating lymphocytes (TILs) into radiation site." (PMID 37259456, 2023). "To identify candidate stroma-derived factors that might influence desmoid tumor cell proliferation, we treated mutant-only cultures with recombinant IGFBP3, PTX3, CCL2, CXCL12, and CHI3L1 in serum-free conditions." (PMID 37377751, 2023). "The binding of CXCL12 to CXCR4 is said to initiate divergent signaling pathways that lead to multiple responses, including the phosphorylation of MEK/ERK signaling cascade and the activation of NF-κB, which is essential for tumor cell survival." (PMID 36826044, 2023). "CXCL12 in the tumor microenvironment is mostly produced by CAF and plays a crucial function in attracting myeloid cells and supporting an immunosuppressive phenotype; inhibition of CXCL12 or its receptor CXCR4 lowers the amount of MDSC in the tumor." (PMID 37007004, 2023). "CAFs secrete soluble factors, which include cytokines, chemokines, and growth factors such as interleukin 6 (IL-6), C-type lectin domain family 3 member B (CLEC3B), C-X-C motif chemokine 12 (CXCL12), and epidermal growth factor (EGF) to transform the TME to support tumor growth." (PMID 37469395, 2023). "Feig and collaborators found that T cells were absent from tumor regions containing cancer cells, which were coated with CXCL12." (PMID 37284199, 2023). "CXCL12 is a homeostatic CXC chemokine involved in the process of proliferation, and tumor spread." (PMID 37035150, 2023). "Moreover, CX3CL1 plays a role in tumor promotion and dissemination in patients with RCC besides CXCL12." (PMID 37021054, 2023). "CXCL12/CXCR4 signal transduction not only promotes dysplasia and stress of tumour tissues, inducing physical barrier for therapeutic agents and T cell penetration, but also functions importantly to promote tumour cell migration, proliferation and invasions." (PMID 37162544, 2023). "In particular, CAF secrete the C-X-C Motif Chemokine Ligand 12 CXCL12 attracting and retaining both myeloid and CD4+/CD25+ T cells in the tumor, ultimately promoting their differentiation to Tregs immune cells and their survival via the expression of T cell interacting proteins." (PMID 37265795, 2023). "CXCL12 (stroma-derived factor-1, SDF-1) is another critical chemoattraction for TAMs recruiting via the CXCL12/CXCR4 pathway, especially for infiltrating areas of hypoxia and tumor invasiveness." (PMID 37012233, 2023). "Moreover, the tumor cell-derived CXCL6, CXCL2, and CCL20, TAM-derived CXCL9/CXCL10, and the stromal cell-derived CXCL12 also contributed to the accumulation of tissue-resident CD103+CD8+TILs in the TME." (PMID 37024870, 2023). "Besides, CAFs, major sources of chemokines, including CXCL12, CCL2 and CXCL1, can recruit MDSCs to tumor sites and promote their differentiation and activation." (PMID 37046312, 2023). "CXCL12, secreted by tumor and stromal cells, regulates plasmacytoid DC trafficking to tumors and integrin α5 and C-X-C Motif Chemokine Receptor 4 (CXCR4) expressed by plasmacytoid DCs and promotes tumor clearance through antigen presentation." (PMID 37895310, 2023).